CHRNG (cholinergic receptor nicotinic gamma subunit)
Description:
After binding acetylcholine, the AChR responds by an extensive change in conformation that affects all subunits and leads to opening of an ion-conducting channel across the plasma membrane.
Synonyms: ACHRG
Tractability: Small molecule: an approved drug acts on it; a high-quality ligand is known; it belongs to a druggable protein family. Antibody: its Gene Ontology location is reachable by antibodies, with high confidence; UniProt places it where antibodies can reach, with medium confidence; UniProt predicts a signal peptide or a membrane-spanning region. PROTAC: a small molecule that binds it is known.
Gene: Protein-coding gene on chromosome 2 (232,539,692 to 232,548,115, forward strand). Ensembl gene ENSG00000196811.
Subcellular location: Postsynaptic cell membrane; Cell membrane
Pathways (Reactome):
Neuronal System: Highly sodium permeable postsynaptic acetylcholine nicotinic receptors
Gene Ontology:
Molecular function: protein binding; acetylcholine receptor activity; acetylcholine-gated monoatomic cation-selective channel activity; channel activity; transmitter-gated monoatomic ion channel activity involved in regulation of postsynaptic membrane potential; extracellular ligand-gated monoatomic ion channel activity; monoatomic ion channel activity; transmembrane signaling receptor activity
Biological process: acetylcholine receptor signaling pathway; calcium ion transport; membrane depolarization; monoatomic ion transmembrane transport; muscle contraction; signal transduction; skeletal muscle contraction; synaptic transmission, cholinergic; cell communication; chemical synaptic transmission, postsynaptic; excitatory postsynaptic potential; monoatomic ion transport; regulation of postsynaptic membrane potential; signaling
Cellular component: acetylcholine-gated channel complex; neuron projection; plasma membrane; synapse; membrane; postsynaptic membrane
Genetic constraint (gnomAD): Loss-of-function variants: 69 observed, 65.56 expected, observed/expected ratio (o/e) 1.05, 90% interval 0.87 to 1.29. The upper end of that interval is the gene's LOEUF score, 1.29, which puts it in group 5 of 6, group 1 being the genes least tolerant of losing a copy. Missense variants: 636 observed, 708.18 expected, observed/expected ratio (o/e) 0.9, 90% interval 0.84 to 0.96. Synonymous variants: 284 observed, 305.13 expected, observed/expected ratio (o/e) 0.93, 90% interval 0.84 to 1.03.
Gene-disease validity (ClinGen):
ClinGen rates the evidence that CHRNG causes each of these diseases.
CHRNG-associated hypo-akinesia disorder of prenatal onset (autosomal recessive): Definitive. A spectrum of presentations resulting from biallelic protein-altering variation in CHRNG.
Homologues: Orthologues: chimpanzee CHRNG (99% identical), macaque CHRNG (97% identical), pig CHRNG (92% identical), mouse Chrng (91% identical), dog CHRNG (90% identical), rat Chrng (90% identical), guinea pig CHRNG (89% identical), rabbit CHRNG (80% identical), tropical clawed frog chrng (61% identical), zebrafish chrng (56% identical). Paralogues in human: CHRNE (49% identical), CHRND (45% identical), CHRNB1 (39% identical), CHRNB2 (37% identical), CHRNB4 (36% identical), CHRNA4 (35% identical), CHRNA2 (33% identical), CHRNA3 (32% identical), CHRNA6 (31% identical), CHRNA1 (31% identical), CHRNA7 (29% identical), CHRNA5 (28% identical), and 33 more.
Diseases named in the same sentence as CHRNG in open-access papers:
CHRNG is named in the same sentence as 41 diseases in open-access papers, as found by Europe PMC text mining. Sharing a sentence is not in itself a finding about the gene and the disease. The quoted sentences say what the papers report.
Escobar syndrome (8 papers, 2019 to 2025). "The presence of an incomplete form of Escobar syndrome suggests that pathogenic variants of CHRNG are likely to be undetermined in patients with distal arthrogryposis." (PMID 36835142, 2023). "Loss-of-function variants of CHRNG cause EVMSP (Escobar syndrome) and LMPS, both of which are characterized by arthrogryposis multiplex congenita (AMC) and pterygium likely due to the embryonic immobility." (PMID 36835142, 2023). "In order to determine the genetic causes of Escobar syndrome in these patients, we first performed Sanger sequencing for mutations associated with the CHRNG gene (NM_005199.5)." (PMID 36292632, 2022). "While CHRNG mutations caused Escobar syndrome for 75 patients of known cases, a number of patients had a genetic etiology associated with variants in the TPM2, CHRND, CHRNA1, MUSK, MYH3, RAPSN, and DOK7 genes." (PMID 36292632, 2022). "Generally, Escobar syndrome is associated with mutations in the CHRNG gene (reported in 75 Escobar patients)." (PMID 36292632, 2022). "Genetic studies have shown that Escobar syndrome is an autosomal recessive disorder, linked in most cases to mutations in the CHRNG gene." (PMID 36292632, 2022). "To date, 83 patients with Escobar syndrome with mutations in CHRNG and TPM2 have been reported in the literature." (PMID 36292632, 2022). "The evolution of the phenotype through the years was crucial to guide the diagnosis: DA5D in pt 9, with billelic variants in ECEL1 that met the ACMG criteria of pathogenicity, and Escobar syndrome in pt 10, with a known pathogenic homozygous variant in CHRNG." (PMID 35052370, 2021). "In a study of seven families with Escobar syndrome (contractions, multiple pterygia, respiratory distress), mutations in the CHRNG gene were detected in 12 family members." (PMID 30808424, 2019). "Biallelic loss of function variants in CHRNG are a well-established cause of Escobar syndrome." (PMID 34440395, 2021).
multiple pterygium syndrome (3 papers, 2015 to 2021). "For instance, curarizing agents are listed with CHRNG which codes for a subunit of the acetylcholine receptor (AChR), and a mutation of which is associated with multiple pterygium syndrome (MPS)." (PMID 34356068, 2021). "Of these four variants, 2 were discarded since within genes already reported to be responsible for phenotypically divergent recessive diseases: KANK2, implicated in palmoplantar keratoderma and woolly hair (MIM 616099) and CHRNG, implicated in multiple pterygium syndrome (MIM 253290)." (PMID 25870235, 2015). "Mutations in the CHRNG encoding the embryonal acetylcholine receptor may cause the non-lethal Escobar variant (EVMPS) and lethal form (LMPS) of multiple pterygium syndrome." (PMID 27245440, 2016).
scoliosis (3 papers, 2019 to 2025). A congenital or acquired spinal deformity characterized by lateral curvature of the spine. "In case 8 (two-sided rocker bottom feet, scoliosis, and spina bifida occulta), compound heterozygous mutations were detected in the CHRNG gene." (PMID 31299979, 2019).
melanoma (2 papers, 2023 to 2024). A malignant, usually aggressive tumor composed of atypical, neoplastic melanocytes. "On the other hand, compared with the low expression of CHRNG, pathways activated in SKCM patients with a high expression of CHRNG mainly concerned muscle contraction activities, which still require further investigation of its relationships with melanoma." (PMID 37404751, 2023). "Results revealed that CHRNA4 (HR 4.263, 95% CI 1.612–11.272, p = 0.003), CHRNG (HR 8.430, 95% CI 1.510–47.067, p = 0.015), melanoma ulceration (HR 1.627, 95% CI 1.061–2.496, p = 0.026), and N2&3 stage (HR 3.709, 95% CI 2.257–6.095, p < 0.001) were independent poor prognostic factors." (PMID 37404751, 2023).
pneumonitis (2 papers, 2023 to 2024). An inflammatory process affecting the lung parenchyma. "In another recent investigation involving individuals with NSCLC who experienced ICI-pneumonitis, there was a rise in IgM antibody levels against ACHRG, the cholinergic receptor nicotinic gamma subunit, from the beginning of treatment to the onset of toxicity in these patients." (PMID 39247203, 2024).
sarcoma (2 papers, 2021). A usually aggressive malignant neoplasm of the soft tissue or bone. "The overexpression of CHRNG indicates the possibility of sarcoma in children." (PMID 34912722, 2021). "Importantly, MYOG and CHRNG were overexpressed in this cluster, indicating that referencing gene expression profiles may assist with the categorization and diagnosis of pediatric sarcomas." (PMID 34131151, 2021).
Diabetes (1 paper, 2008). "We sequenced CHRNA1, CHRND and CHRNG in 24 Amish subjects from the Amish Family Diabetes Study (AFDS) and identified 20 variants." (PMID 18625075, 2008).
generalized dystonia (1 paper, 2022). "In eight patients with generalized dystonia from infancy, the mutation of PIGA, TCF4, CHRNG, SLC16A2, KCNQ2, NACC1, CTNNB1, or ARSA gene were found to be causative." (PMID 35719373, 2022).
myasthenia gravis (1 paper, 2022). Myasthenia gravis (MG) is a rare, clinically heterogeneous, autoimmune disorder of the neuromuscular junction characterized by fatigable weakness of voluntary muscles. "Other interesting data were the lower gene levels for some of the components of the acetylcholine receptor (CHRNB1, CHRNA1 and CHRNG) that may result in a significant reduction of the amplitude of the transmission signal, as has already been demonstrated for myasthenia gravis patients." (PMID 36359747, 2022).
Stillbirth (1 paper, 2016). Death of the fetus in utero after at least 22 weeks of gestation. "Although individuals with CHRNG mutations can survive, there is an increased frequency of abortions and stillbirth in their families." (PMID 27245440, 2016).
cancer (1 paper, 2023). A tumor composed of atypical neoplastic, often pleomorphic cells that invade other tissues. "Still, our comprehensive bioinformatics analysis of cancer–nerve crosstalk-associated genes in SKCM constructed a valuable prognostic model based on eight genes (GRIN3A, CCR2, CHRNA4, CSF1, NTN1, ADRB1, CHRNB4, and CHRNG) and common clinical characteristics." (PMID 37404751, 2023).
tumor (1 paper, 2019). "CHRNA5, CHRNA10, CHRNB4, CHRND, CHRNE, and CHRNG, however, were not expressed at levels significantly different from the non-tumor control samples." (PMID 31590360, 2019).
CHRNG also shares sentences with these, for which no sentence is quoted: arthrogryposis (3 papers); Alpha-thalassemia (1); Arrhythmogenic right ventricular dysplasia (1); arthrogryposis multiplex congenita (1); Birk-Barel syndrome (1); brain malformations (1); channelopathies (1); Chediak-Higashi syndrome (1); Cohen syndrome (1); congenital myasthenic syndrome (1); congenital secretory chloride diarrhea 1 (1); deafness (1); dermatitis (1); epilepsy (1); genetic disorder (1); Hepatitis (1); Intellectual disability (1); myasthenia (1); myopia (1); neurodegenerative disease (1); neuromuscular disease (1); neuropathy (1); Palmoplantar keratoderma (1); Respiratory distress (1); rhabdomyosarcoma (1); Rubinstein-Taybi syndrome 1 (1); Spina bifida occulta (1); spondylometaphyseal dysplasia (1); temtamy syndrome (1).